SLC26A3 (solute carrier family 26 member 3)
Diseases named in the same sentence as SLC26A3 in open-access papers (continued):
Sharing a sentence is not in itself a finding about the gene and the disease.
Diarrhea (4 papers, 2019 to 2025). Abnormally increased frequency (usually defined as three or more) loose or watery bowel movements a day. "Congenital chloride diarrhea (CLD; OMIM #214700) is an autosomal recessive disease caused by mutations in the solute carrier family 26 member 3 (SLC26A3 alias DRA) gene." (PMID 39992989, 2025). "In the ileum and proximal colon, absorption of sodium chloride occurs predominantly via the coupled action of SLC26A3 and SLC9A3, which is disrupted in congenital sodium diarrhea (CSD) and linked to IBD risk." (PMID 39992989, 2025). "Congenital chloride diarrhea, first described in 1945, is related to a loss-of-function (LOF) mutation in the solute carrier family 26 member 3 (SLC26A3)." (PMID 40649913, 2025). "SLC26A3 interacts with several ion transporters linked to intestinal inflammation, such as cystic fibrosis transmembrane conductance regulator (CFTR) and solute carrier family 9 member 3 (SLC9A3) causing congenital sodium diarrhea." (PMID 39992989, 2025).
Infertility (4 papers, 2015 to 2022). "We observed that, altogether, 25 men with idiopathic infertility carried heterozygous variants in the coding region of the SLC26A3 gene (GenBank: NM_000111.2), the frequency of heterozygosity being 3.7-fold higher in infertile men than in controls (8.8% vs. 2.4%, respectively; P = 0.007)." (PMID 29079751, 2017). "Accordingly, we studied the influence of SLC26A3 on idiopathic infertility by sequencing exons of SLC26A3 in 283 infertile and 211 control men." (PMID 29079751, 2017). "The fact that even CLD-related sperm findings for sperm motility and seminal plasma pH vary highlights the clinical phenotype of subfertility—rather than complete infertility—in relation to SLC26A3 mutations." (PMID 29079751, 2017).
male infertility (4 papers, 2016 to 2023). The inability of the male to effect fertilization of an ovum after a specified period of unprotected intercourse. "The p.Asp688His mutation is localized in the CFTR-interacting STAS domain of SLC26A3 and enriched in Finland, showing a significant association with male infertility in comparison with 6,572 Finnish (P < 0.05) and over 120,000 global alleles (P < 0.0001) (ExAC database)." (PMID 29079751, 2017). "SLC26A3 knockout mice also exhibit subfertility, however, whether SLC26A3 is associated with other forms of defects in fertility other than male infertility remains unexplored." (PMID 27346053, 2016). "Further studies on members of the SLC26 family are likely to provide important data on the pathogenesis of male infertility and the action of the SLC26A3/CFTR complex in sperm cells." (PMID 29079751, 2017). "The importance of both CFTR and SLC26A3 functions in the physiology of male fertility is supported by their molecular interaction, by the male infertility phenotypes of CF and CLD, and by their role in rodent sperm motility and capacitation." (PMID 29079751, 2017). "Homozygous SLC26A3 mutations cause congenital chloride diarrhea with male subfertility, while homozygous CFTR mutations cause cystic fibrosis with male infertility." (PMID 29079751, 2017). "Whereas the impact of CFTR defects on male infertility has been extensively studied, the effects of SLC26A3 variants on male infertility without CLD remain poorly understood." (PMID 29079751, 2017). "Indeed, nearly all pathogenic gene variants that have been described to contribute to asthenozoospermia and male infertility in humans (CASTSPER, SLC26A3, SLC26A8, SLC9C1, VDAC, SLO3) were supported by studies using KO mouse models that show a similar phenotype and pathology." (PMID 35409285, 2022).
Alkalosis (3 papers, 2021 to 2022). Depletion of acid or accumulation base in the body fluids. "It was reported previously that intestinal SLC26A3 was in charge of bicarbonate ion secretion and chloride ion and water absorption and that patients with SLC26A3 mutations would suffer from acidic diarrhea and systemic alkalosis." (PMID 34783577, 2021). "We note that diarrhea and metabolic alkalosis in knockout mice and in humans with DRA mutations occur in the setting of chronic and complete SLC26A3 loss of function, which probably accounts for their absence in the 7-day treatment studies." (PMID 35608921, 2022).
asthenozoospermia (3 papers, 2017 to 2024). "Consistent with this, most individuals carrying heterozygous variants in SLC26A8 and SLC26A3 also presented with mild asthenozoospermia phenotype." (PMID 35409285, 2022). "This study suggests that human OAT and asthenozoospermia are associated with the heterozygous mutation c.2062 G > C (p.Asp688His) in the regulatory STAS domain of SLC26A3." (PMID 29079751, 2017). "However, heterozygosity for a mutation of the STAS domain of SLC26A3 has already been shown to result in asthenozoospermia (SLC26A3-p.Asp688His)." (PMID 39676174, 2024). "Importantly pathogenic gene variants in SLC26A8 and SLC26A3 were reported to induce human asthenozoospermia and male subfertility." (PMID 35409285, 2022). "Unlike the sperm-specific SLC26A8, the loss of which causes complete lack of sperm motility and reduced sperm fertilization potential in mice and asthenozoospermia in humans, the role of SLC26A3 in regulation of male fertility is more complex." (PMID 29079751, 2017).
breast carcinoma (3 papers, 2014 to 2018). "Butyrate induced the transcription of SLC16A3, SLC26A3, and HIF1A in sheep ruminal epithelia, human breast cancer, and colon cell lines." (PMID 30258628, 2018). "However, some general trends are observed across all breast cancer subtypes: SLC4A1, SLC4A4, SLC26A3, and SLC26A4 seem to be consistently down-regulated, while SLC4A5 is up-regulated, in all breast cancer subtypes compared to normal breast tissue." (PMID 24795638, 2014).
Congenital chloride diarrhoea (3 papers, 2010 to 2024). "Congenital chloride diarrhoea (CCD) is a rare autosomal recessive disease causing severe electrolyte imbalances because of mutation in the intestinal Cl−/HCO3− exchanger gene SLC26A3 (solute carrier family 26 member 3)." (PMID 38704545, 2024). "Mutation of the SLC26A3 gene results in an autosomal recessive disorder, congenital chloride diarrhoea (CLD), which enhances colonic proliferation and up‐regulation of ion transporters in the colon." (PMID 32662230, 2020). "Thus, inflammation reduces the intestinal expression of SLC26A3 a chloride transporter that is mutated in patients with congenital chloridorrhea." (PMID 20398419, 2010). "Congenital chloride diarrhoea (CCD) is an autosomal recessive condition that causes secretory diarrhoea and potentially deadly electrolyte imbalances in infants because of solute carrier family 26 member 3 (SLC26A3) gene mutations." (PMID 38704545, 2024).
cystic fibrosis (3 papers, 2017 to 2026). Autosomal recessive disorder caused by pathogenic variants in the CFTR gene (cystic fibrosis transmembrane conductance regulator), which encodes a chloride and bicarbonate channel expressed in epithelial cells, and follow the diagnosis criteria. "Human colonic and rectal organoids from healthy controls and cystic fibrosis patients with F508del mutations were studied in the proliferative state with high endogenous CFTR expression and inducible SLC26A3 overexpression." (PMID 41498431, 2026).
Hyperoxaluria (3 papers, 2022 to 2023). Increased excretion of oxalates in the urine. "A small-molecule inhibitor of the intestinal anion exchanger SLC26A3 has been identified for the treatment of hyperoxaluria." (PMID 37371749, 2023). "By selectively inhibiting SLC26A3-mediated oxalate absorption, this inhibitor has the potential to alleviate the burden of oxalate-related complications and improve the management of hyperoxaluria." (PMID 37371749, 2023). "Thus, there is uncertainty about whether SLC26A3 mediates physiologically significant oxalate transport and, therefore, whether SLC26A3 inhibition would be therapeutically beneficial for conditions associated with hyperoxaluria." (PMID 35608921, 2022). "Humans with loss-of-function SLC26A3 mutations, therefore, have an estimated 40%–70% lower urinary oxalate excretion compared with healthy controls, further supporting the potential therapeutic utility of pharmacological SLC26A3 inhibition in hyperoxaluria." (PMID 35608921, 2022). "Our findings support a major role of SLC26A3 in intestinal oxalate absorption and suggest the therapeutic utility of SLC26A3 inhibition for treatment of hyperoxaluria and prevention of calcium oxalate nephrolithiasis." (PMID 35608921, 2022). "Over the past decade, researchers have suggested that SLC26A3 may serve as a therapeutic target to treat hyperoxaluria and prevent CaOx urolithiasis." (PMID 37304821, 2023). "Testing of SLC26A3 inhibitors in models of hyperoxaluria with steatorrhea and increased luminal bile acids, such as Roux-en-Y gastric bypass in rats, may be informative." (PMID 35608921, 2022).
kidney stones (3 papers, 2022 to 2023). "In mice, SLC26A6 loss of function impairs intestinal oxalate secretion and causes nephrolithiasis, whereas SLC26A3 loss of function impairs colonic oxalate absorption and reduces urinary oxalate excretion by 70%." (PMID 35608921, 2022). "By reducing intestinal oxalate absorption and, hence, directing oxalate excretion to the stool, SLC26A3 inhibition provides a potentially novel, targeted approach to reducing urinary oxalate excretion in nephrolithiasis and enteric hyperoxaluria." (PMID 35608921, 2022).
Crohn disease (2 papers, 2015 to 2020). A gastrointestinal disorder characterized by chronic inflammation involving all layers of the intestinal wall, noncaseating granulomas affecting the intestinal wall and regional lymph nodes, and transmural fibrosis. "Our results showed a downregulation of SLC26A3 gene expression in the colonic mucosa from patients with active UC and one study reported the altered transportome profile in patients with Crohn's disease." (PMID 32410873, 2020).
Arrhythmia (1 paper, 2021). Any cardiac rhythm other than the normal sinus rhythm. "Other RV-specific transcriptional changes, which may contribute to the observed phenotype, included underexpression of Slc26a3, which controls intracellular pH and may impact Ca-cycling, and upregulation of Mcoln2, which may participate in Ca-overload and potential arrhythmia." (PMID 34204946, 2021).
asthma (1 paper, 2015). "Of these, five missense mutations (one each in FAM134B, NPC1L1, IKZF1, SLC26A3 and GSDMB) showed evidence of association with asthma in the combined sample, two of which (IKZF1 and SLC26A3) were more significant in the African ancestry sample." (PMID 25591454, 2015).
cervical cancer (1 paper, 2025). A primary or metastatic malignant neoplasm involving the cervix. "SLC26A3 is identified as a potential prognostic and diagnostic indicator for lymph node metastasis of cervical cancer (CC) patients." (PMID 40066698, 2025).
colorectal adenocarcinoma (1 paper, 2022). The most common type of colorectal carcinoma. "In conclusion, by integrating WGCNA and differential gene expression analysis, our study screened five important survival-related genes (SLC26A3, GUCA2A, CLCA4, CLCA1, and AQP8) and a 3-gene risk model with the potential to predict the prognosis of colorectal adenocarcinoma." (PMID 35693937, 2022).
gallstones (1 paper, 2024). Solid crystalline precipitates in the biliary tract, usually formed in the gallbladder, resulting in the condition of cholelithiasis. "The results indicated that AC004692.4, HECW1-IT1, SFRP4, and COMP were significantly higher expressed in gallstone samples, whereas LINC01564, SLC26A3, RP1-27K12.2, and GSTA2 were markedly lower expressed in gallstone samples compared to control samples." (PMID 38808330, 2024). "Furthermore, using RT-qPCR, we observed significant upregulation of AC004692.4, HECW1-IT1, SFRP4, and COMP, while LINC01564, SLC26A3, RP1-27K12.2, and GSTA2 exhibited marked downregulation in gallstone samples." (PMID 38808330, 2024).
Hydrocephalus (1 paper, 2021). Hydrocephalus is an active distension of the ventricular system of the brain resulting from inadequate passage of CSF from its point of production within the cerebral ventricles to its point of absorption into the systemic circulation. "Four genes were found to be involved in four cases each: the RAPSN gene related to fetal akinesia syndrome II, the SLC26A3 gene related to congenital chloride diarrhea, the L1CAM gene related to hydrocephalus with X-linked inherence, and the FOXC2 gene related to lymphedema-distichiasis syndrome." (PMID 34682862, 2021).
Meconium ileus (1 paper, 2015). Obstruction of the intestine due to abnormally thick meconium. "However, a GWAS study of 3763 CF patients failed to reveal SLC26A3 as a strong modifier gene for the neonatal intestinal CF phenotype of meconium ileus." (PMID 26157392, 2015).
pancreatic cancer (1 paper, 2007). "We used T-84 cells, a human colonic cell line, as a positive control for SLC26A3, and Capan-1 cells, a metastatic human pancreatic cancer cell line, for SLC26A9." (PMID 17635413, 2007).
urolithiasis (1 paper, 2023). Stone(s) within the urinary tract. "These lines of evidence suggests that abnormal SLC26A3 expression, a risk factor for urolithiasis, is related to other mechanisms of urolithogenesis in addition to the regulation of oxalate metabolism." (PMID 37304821, 2023). "However, another study showed that SLC26A3 overexpression in the murine intestine did not increase oxaluria and also reduced renal CaOx deposition, suggesting a role in preventing rather than promoting urolithiasis." (PMID 37304821, 2023).
tumor (18 papers, 2009 to 2026). "Conversely, gene expressions previously linked to tumor cell differentiation and favorable outcome, such as SLC26A3, PIGR, CKB and FABP1, were highly expressed in GPA33-high cancer cells." (PMID 39472498, 2025). "Our study indicates that SLC26A3 undergoes lactylation in the acidic tumor microenvironment, which decreases SLC26A3 stability and expression." (PMID 41617682, 2026). "The SLC26 family, including SLC26A3, has tumor-suppressive effects in colorectal cancer when downregulated." (PMID 41425581, 2025). "Collectively, these findings indicate that SLC26A3 acts as a tumor suppressor in CRC and inhibits the malignant biological behaviors of CRC cells." (PMID 37573425, 2023). "For the subcutaneous tumor, the IHC revealed that the expression level of IκB was positively correlated with SLC26A3 protein levels." (PMID 37573425, 2023). "For the orthotopic transplantation tumor, IHC analysis showed that in solid tumors with stable overexpression of SLC26A3, the expression level of IκB was higher compared to the control group." (PMID 37573425, 2023). "Earlier studies also suggested possible roles of SLC26A3 in tumor suppression, intestinal barrier function, and inflammation, perhaps due to altered intracellular pH." (PMID 35608921, 2022). "SLC26A3 downexpressed in CRC played a tumor suppressor role and was expected to be a candidate epithelial marker in CRC." (PMID 32351322, 2020). "These were Defcr4, S100A9, Igfbp5, Slc30a2 and Lgr5 (leucine-rich repeat containing G protein coupled receptor 5) which were up-regulated and Mptx, Slc26a3, Retnla, Muc2 and Hpgd (hydroxyprostaglandin dehydrogenase 15) which were down-regulated in tumours." (PMID 20459814, 2010). "We hypothesize that SLC26A3 plays a critical role in tumor inhibition via the SLC26A3/NHERF2-IκB/NF-κB/p65-SLC26A3 feedback loop." (PMID 37573425, 2023). "As a bicarbonate transporter, SLC26A3 may also have effects on tumor suppression via its ion transport domain." (PMID 37573425, 2023). "Collectively, our results suggest that SLC26A3 acts as a tumor suppressor in CRC and downregulation of its expression may serve as a molecular biomarker for identifying CRC patients at high risk for poor prognosis." (PMID 37573425, 2023). "According to the HPA database, the protein levels of SLC26A3, GUCA2A, CLCA4, CLCA1, and AQP8 in tumor tissues were all significantly lower than that in normal tissues." (PMID 35693937, 2022). "We detected significant previously undescribed underexpression in CRC for genes SLC26A3, TPM1 and DCN, with a suggested tumour suppressor role." (PMID 19678923, 2009). "When we looked for the function of these genes, we found that three (SLC26A3, TPM1, and DCN) of them play a tumour suppressor role." (PMID 19678923, 2009). "So far, SLC26A3, DCN and TPM1 genes have been suggested to have tumour suppressor properties." (PMID 19678923, 2009). "Importantly, SLC26A3 is down-regulated in CRC tissues, and we identified it as a significantly down-regulated protein in human CRC that may influence tumor progression through the NF-κB signaling pathway." (PMID 37573425, 2023). "Since SLC26A3 is expressed in colonic epithelium but not in blood cells, detection of circulating tumor cells by identification of SLC26A3 mRNA was suggested as a screening method for CRC, but the specificity has so far been too low for SLC26A3 to qualify as a clinically useful marker." (PMID 24795638, 2014).
cancer (10 papers, 2009 to 2025). A tumor composed of atypical neoplastic, often pleomorphic cells that invade other tissues. "In combination, these findings suggest multiple possible roles of SLC26A3 in cancer development, and additional experimental investigations are required to further our mechanistic understanding." (PMID 24795638, 2014). "Since SLC26A3 can remove HCO−3 from cells, it is possible that lower expression of SLC26A3 reduces the net acid load on the cells and eases the elimination of acidic waste products produced by cancer cell metabolism." (PMID 24795638, 2014). "Since cancer cells are generally dedifferentiated compared to normal epithelial cells, however, it cannot currently be excluded that reduced expression of SLC26A3 in colorectal adenocarcinomas is a consequence of the dedifferentiated state rather than a mechanistic cause of malignant development." (PMID 24795638, 2014). "SLC26A3 has, furthermore, been proposed to modify cellular growth: heterologous expression of SLC26A3 induces growth suppression in various cancer cell lines while SLC26A3 knockout mice display altered morphology of the colonic mucosa with an expanded proliferative zone." (PMID 24795638, 2014). "The strongest evidence for involvement of HCO−3 transporters in human cancer has been provided for NBCn1 (SLC4A7) and DRA (SLC26A3)." (PMID 24795638, 2014). "In conclusion, we detected significant under-expression of genes SLC26A3, TPM1, DCN and CALM3 in CRC, providing further evidence of their decreased mRNA expression and thus implicating them in the development of this type of cancer." (PMID 19678923, 2009). "C1-2 cells lacked reported cancer cell functional alterations, suggesting that they are enriched in normal epithelial cells, and C1 cells expressed markers of mature colonocytes (GUCA2B, SLC26A3 and CA1)." (PMID 36209225, 2022).
infection (7 papers, 2014 to 2025). The state of being infected such as from the introduction of a foreign agent such as serum, vaccine, antigenic substance or organism. "In this population, ion transporters including Slc26a3 and Ca4 were downregulated post-infection, indicating that infected enterocytes sensed C. rodentium and altered their gene expression profile." (PMID 41361166, 2025). "In addition, higher expression of solute carrier family genes (Slc13a1, Slc26a3, Slc2a2, Slc40a1, Slc5a1, and Slc6a19) was seen in the gastric tissue of Muc1−/− mice compared with WT at sham and 8 h infection." (PMID 32793510, 2020).
adenocarcinoma (5 papers, 2010 to 2025). A common cancer characterized by the presence of malignant glandular cells. "(C) Immunohistochemistry (IHC) staining showing the protein expression of SLC26A3 in surgically resected adenocarcinoma (ADC) samples which are classified as early stages (International Federation of Gynecology and Obstetrics [FIGO] stage I–IIA) and late stages (FIGO stage IIIC1–2p)." (PMID 40066698, 2025).